CMTM6 (CKLF like MARVEL transmembrane domain containing 6)
Description:
Master regulator of recycling and plasma membrane expression of PD-L1/CD274, an immune inhibitory ligand critical for immune tolerance to self and antitumor immunity. Associates with both constitutive and IFNG-induced PD-L1/CD274 at recycling endosomes, where it protects PD-L1/CD274 from being targeted for lysosomal degradation, likely by preventing its STUB1-mediated ubiquitination. May stabilize PD-L1/CD274 expression on antigen presenting cells and potentiates inhibitory signaling by PDCD1/CD279, its receptor on T-cells, ultimately triggering T-cell anergy.
Synonyms: CKLFSF6; FLJ20396; PRO2219
Tractability: Antibody: UniProt places it where antibodies can reach, with high confidence; its Gene Ontology location is reachable by antibodies, with high confidence; UniProt predicts a signal peptide or a membrane-spanning region. PROTAC: ubiquitination databases record sites on it.
Gene: Protein-coding gene on chromosome 3 (32,474,175 to 32,502,852, reverse strand). Ensembl gene ENSG00000091317.
Subcellular location: Cell membrane; Early endosome membrane; Recycling endosome membrane
Subcellular location (Human Protein Atlas): Vesicles
Pathways (Reactome):
Immune System: Neutrophil degranulation
Gene Ontology:
Molecular function: protein binding
Biological process: endocytic recycling; protein transport; regulation of protein stability
Cellular component: early endosome membrane; membrane; plasma membrane; recycling endosome membrane; azurophil granule membrane; specific granule membrane
Genetic constraint (gnomAD): Loss-of-function variants: 6 observed, 8.94 expected, observed/expected ratio (o/e) 0.67, 90% interval 0.37 to 1.32. That is too few expected variants to judge how well the gene tolerates losing a copy. Missense variants: 169 observed, 162.74 expected, observed/expected ratio (o/e) 1.04, 90% interval 0.92 to 1.18. Synonymous variants: 90 observed, 68.52 expected, observed/expected ratio (o/e) 1.31, 90% interval 1.11 to 1.57.
Homologues: Orthologues: chimpanzee CMTM6 (99% identical), macaque CMTM6 (95% identical), guinea pig CMTM6 (85% identical), mouse Cmtm6 (83% identical), dog CMTM6 (79% identical), rat Cmtm6 (73% identical), tropical clawed frog cmtm7 (40% identical), zebrafish cmtm6 (34% identical), Caenorhabditis elegans F28H1.4 (17% identical), Caenorhabditis elegans F47B3.3 (13% identical). Paralogues in human: CMTM4 (32% identical), CMTM7 (22% identical), CMTM3 (20% identical), CMTM5 (19% identical), MARVELD1 (17% identical), PLP2 (16% identical), MALL (15% identical), MAL2 (15% identical), MAL (14% identical), CMTM8 (13% identical), CMTM1 (13% identical), PLLP (12% identical), and 2 more.
Diseases named in the same sentence as CMTM6 in open-access papers:
CMTM6 is named in the same sentence as 69 diseases in open-access papers, as found by Europe PMC text mining. Sharing a sentence is not in itself a finding about the gene and the disease. The quoted sentences say what the papers report.
hepatocellular carcinoma (19 papers, 2019 to 2024). A malignant tumor that arises from hepatocytes. "Researches have shown a significant positive association between CMTM6 and PD-L1 expression in gastric cancer, glioma, hepatocellular carcinoma, non-small cell lung cancer, and lung squamous carcinoma." (PMID 37726578, 2023). "Recent studies have shown that CMTM6 plays an oncogenic role and is associated with poor prognosis in gliomas, hepatocellular carcinoma, and LUAD." (PMID 33552963, 2020). "In colorectal cancer, high CMTM6 levels are associated with an inflamed tumor microenvironment, while in hepatocellular carcinoma, CMTM6 inhibits cell proliferation by preventing p21 ubiquitination." (PMID 38067301, 2023). "On the contrary, the expression of CMTM6 in hepatocellular carcinoma and esophageal cancer tissues is lower than that in normal tissues, which indicates that CMTM6 expression is different in different tissues." (PMID 35845949, 2022). "Knockdown of CMTM6 in hepatocellular carcinoma (HCC) cells also inhibits cell proliferation and affects tumor recurrence." (PMID 36698778, 2022). "CMTM6 expression was associated with poor prognosis in hepatocellular carcinoma (HCC)." (PMID 32874775, 2020). "CMTM6 was related to OS in several cancer types, like glioblastoma and hepatocellular carcinoma." (PMID 38542462, 2024). "However, the role of CMTM6 in hepatocellular carcinoma is more complicated, as CMTM6 was shown to play both a tumor-suppressive role and a tumor-promoting role in hepatocellular carcinoma." (PMID 39218981, 2024). "Studies have shown that CMTM6 may serve as an unfavorable prognostic factor in glioma and a favorable prognostic factor in hepatocellular carcinoma, and the relationship between the expression of PD-L1 and the prognosis of CRC is still controversial." (PMID 33818637, 2021). "However, the roles of CMTM6 in hepatocellular carcinoma (HCC) are largely unknown." (PMID 33757532, 2021). "At the protein level evaluated by immunohistochemistry, highly expressed CMTM6 indicates poor prognosis in gastric cancer, HNSCC, hepatocellular carcinoma." (PMID 34680324, 2021). "CMTM6 has been shown to have oncogenic properties and be highly expressed in various tumors such as head and neck squamous cell carcinoma (HNSCC), glioma, colorectal cancer, ovarian cancer, oral squamous cell carcinoma (OSCC), hepatocellular carcinoma (HCC), and renal cancer." (PMID 35958549, 2022).
glioma (17 papers, 2020 to 2024). A benign or malignant brain and spinal cord tumor that arises from glial cells (astrocytes, oligodendrocytes, ependymal cells). "In this paper, we analyzed the expression of CMTM6 in pan-cancer and glioma, its interactions and associated factors by bioinformatics." (PMID 36698778, 2022). "CMTM6 overexpression was associated with poor prognosis in gliomas." (PMID 32874775, 2020). "Interestingly, we found that CMTM6/CMTM4 and PD-L1 co-localized in macrophages are associated with lower OS in glioma, suggesting that CMTM6/CMTM4 may be specific companion diagnostic biomarkers for immunotherapy in gliomas." (PMID 35983975, 2022). "CMTM6 expression was also upregulated in advanced malignant glioma, and it was responsible for the poor prognosis of patients with glioma." (PMID 38223763, 2024). "We analysed the protein expression of 12 of the 14 differentially expressed endosomal recycling regulators in this glioma proteomics inventory (CMTM6 and KDELR1 were missing from this dataset)." (PMID 38638676, 2024). "In summary, we showed that CMTM6/CMTM4 expression is significantly correlated with PD-L1 in gliomas, which corresponds to the role of CMTM6/CMTM4 in the stabilization of PD-L1 in tumor cells." (PMID 35983975, 2022). "CMTM6 mRNA level is significant higher while CMTM4 mRNA level is sharply lower in glioma than in normal tissue." (PMID 35983975, 2022). "Currently, most results indicated that CMTM6 helps to establish an immunosuppressive microenvironment in many tumors, such as gliomas, renal carcinomas and colorectal cancer (CRC)." (PMID 35958549, 2022). "The result indicated that the levels of CMTM3, CMTM6, CMTM7, CMTM8, and CKLF were much higher in IDH-WT than in IDH-mutated gliomas in the TCGA database (p < 0.001)." (PMID 35252165, 2022). "KEGG pathway analysis showed that CMTM6 coexpressed genes were remarkedly enriched in the ribosome, neurotrophin signaling pathway, and pathways in prostate cancer and glioma." (PMID 35174213, 2022). "Studies have shown that CMTM6 is abnormally expressed in colorectal cancer, lung cancer, and glioma." (PMID 35845949, 2022). "Previous studies have shown that CMTM6 is elevated in colorectal cancer, non-small-cell lung cancer, glioma, melanoma, and other tissues." (PMID 35845949, 2022). "Cox model analysis showed that CMTM6 was an independent prognostic factor of glioma, which indicated that CMTM6 played an important role in tumor invasion and progression." (PMID 33509216, 2021). "At the mRNA level, a high level of CMTM6 is correlated with better survival in gastric cancer, colorectal cancer, while high level of CMTM6 is correlated with worse survival in gliomas." (PMID 34680324, 2021). "It has been reported that CMTM6 is highly expressed in non-small-cell lung cancer, glioma, head and neck squamous cell carcinoma and so on." (PMID 33818637, 2021). "CMTM6 is important for regulating T-cell activation and antitumor responses and is a promising target for developing immunotherapy of gliomas." (PMID 32874775, 2020). "CMTM6 expression in gliomas was previously correlated with poor prognosis, and its expression was positively correlated with inhibitory T-cell expression." (PMID 33552963, 2020). "A recent study involving RNA-seq data sets revealed that CMTM6 expression is correlated with poor prognosis in human gliomas, possibly due to the inhibition of T-lymphocyte-mediated antitumor immunity." (PMID 32596272, 2020). "Thus, in this study we evaluated the expressions of CMTM6 and CMTM4 in human glioma samples to assess its association with prognosis." (PMID 35983975, 2022). "In this paper, we have performed a detailed analysis and validation of the role of CMTM6 in GBM using bioinformatics analysis and in vitro experiments to demonstrate that CMTM6 may be a potential target for glioma therapy." (PMID 36698778, 2022).
glioma (continued). "Results showed that the expression level of CMTM1, CMTM3, CMTM6, CMTM7, CMTM8, and CKLF was elevated in high-grade gliomas (grade III; p < 0.01)." (PMID 35252165, 2022). "As illustrated, the expression of CMTM3, CMTM6, CMTM7, CMTM8, and CKLF in Grade II and III gliomas showed similar tendency as that in TCGA and CGGA databases." (PMID 35252165, 2022). "In this study, it was found that CMTM6, CMTM7, CMTM8, and CKLF were highly expressed in grade III and IDH-WT gliomas." (PMID 35252165, 2022). "CMTM6 promoted tumor proliferation, migration, and invasion in various tumors, such as RCC, gliomas, and HCC." (PMID 35958549, 2022). "Therefore, CMTM6 may be involved in tumorigenesis in gliomas." (PMID 35983975, 2022). "CMTM6 mRNA level is increased while CMTM4 mRNA level is decreased as pathological grades increase, which indicates glioma prognosis." (PMID 35983975, 2022). "Furthermore, CMTM6 expression was positively correlated with PD-L1 expression in various cancers including HNSCC, lung cancer, gliomas, gastric cancer, and colon cancer." (PMID 35958549, 2022). "These bioinformatics data suggest that CMTM6 and CMTM4 likely play an important role in gliomas." (PMID 35983975, 2022). "Most have previously been proposed as biomarkers in a specific tumor (or tumor-related condition): C15orf48 in esophageal cancer, NF2 in neurofibromatosis, CMTM6 in renal adenocarcinoma, PLEK2 in lung adenocarcinoma, RRM2 in glioma, HOXA1 in breast and gastric cancers, and SAA2 in renal cancer." (PMID 34204789, 2021).
head and neck squamous cell carcinoma (16 papers, 2020 to 2025). A squamous cell carcinoma that arises from any of the following anatomic sites: lip and oral cavity, nasal cavity, paranasal sinuses, pharynx, larynx, and salivary glands. "Our data was in line with other studies indicating that increased CMTM6 expression was presented in gliomaand Head and Neck Squamous Cell Carcinoma, and CMTM6 positivity was associated with shorter DFS and OS." (PMID 32770259, 2021). "Additionally, it has been reported that elevated CMTM6 in head and neck squamous cell carcinoma and glioma is associated with a poor prognosis, and a potential therapeutic target for renal clear cell carcinoma." (PMID 32770259, 2021). "A previous study reported that CMTM6 is involved in EMT regulation in head and neck squamous cell carcinoma; however, whether CMTM6 is implicated in EMT in HCC cells is largely unknown." (PMID 33757532, 2021). "In addition, a significant association between higher CMTM6 expression and poorer relapse-free survival in esophageal squamous cell carcinoma, head and neck squamous cell carcinoma, and lung squamous cell carcinoma was observed from Kaplan-Meier plot analysis." (PMID 33434185, 2021). "Silencing of CMTM6 in head and neck squamous cell carcinoma (HNSCC) reduces β-catenin expression, inhibits stem cell properties, suppresses epithelial-to-mesenchymal transition (EMT) and cell proliferation, and promotes CD8+ and CD4+ t-cell infiltration." (PMID 36698778, 2022). "So far, dysregulation of the CMTM6 gene has been reported in many cancers, including head and neck squamous cell carcinoma, metastatic melanoma, non–small cell lung cancer, and triple-negative breast cancer." (PMID 35174213, 2022). "Targeting CMTM6 suppresses stem cell-like properties and enhances antitumor immunity in head and neck squamous cell carcinoma." (PMID 33818637, 2021). "CMTM4 is closely related to CMTM6 and regulates PD-L1 expression in a similar way in head and neck squamous cell carcinoma and a CMTM6-depleted lung cancer cell line." (PMID 34680324, 2021). "Although previous studies have reported the overexpression of CMTM6 in breast cancer, liver cancer, and head and neck squamous cell carcinoma, its specific function and molecular mechanism in promoting CC remain unclear." (PMID 40761779, 2025). "We retrospectively analyzed 129 treatment-naïve head and neck squamous cell carcinomas (HNSCCs) for the expression of programmed death ligand 1 (PD-L1), CKLF-like MARVEL transmembrane domain-containing 6 (CMTM6), tumor-infiltrating leukocytes (TILs), and tumor-associated macrophages (TAMs)." (PMID 39630300, 2024). "Besides, CMTM6 was recently reported as stemness regulator in head and neck squamous cell carcinoma." (PMID 35304440, 2022). "In head and neck squamous cell carcinoma (HNSCC), the downregulation of CMTM6 induces a decrease in PD-L1, especially in the tumor intrinsic expression." (PMID 36358792, 2022). "Another study demonstrated that CMTM6 knockdown reduced the expression of PD-L1 and increased the infiltration of CD8+ and CD4+ T cells, which enhanced antitumor immunity in head and neck squamous cell carcinoma." (PMID 38223763, 2024). "Among them, in head and neck squamous cell carcinoma (HNSCC), downregulation of CMTM6 not only decreases PD-L1 expression but also promotes infiltration of CD4+ and CD8+ T cells." (PMID 36698778, 2022). "However, some studies have revealed an upregulated expression of CMTM6 in HCC, CRC and head neck squamous cell carcinoma (HNSCC), facilitating the development of malignant diseases." (PMID 40179060, 2025).
melanoma (16 papers, 2020 to 2025). A malignant, usually aggressive tumor composed of atypical, neoplastic melanocytes. "Elevated expression of CMTM6 has been associated with poor prognosis, including reduced survival rates and increased risk of tumor recurrence in several cancer types, such as lung cancer, melanoma, and colorectal cancer." (PMID 40191195, 2025). "For example, CMTM6 expression was significantly higher in OSCC than in adjacent tissues and is widely expressed in melanoma, which is associated with a good prognosis." (PMID 36698778, 2022). "Depletion of CMTM6 in melanoma significantly reduces PD-L1 expression and promotes CD8+ T cell activity." (PMID 35958549, 2022). "CMTM6 has also been validated to inhibit T cell activation and antitumor responses in mouse melanoma models." (PMID 35958549, 2022). "An immunohistochemical analysis using cross-reactive antibodies revealed that canine malignant melanoma and osteosarcoma express CMTM6, CMTM4, and PD-L1 simultaneously." (PMID 32596272, 2020). "CKLF-like MARVEL transmembrane domain containing protein 6 (CMTM6) is a major regulator of PD-L1 expression in cell lines of melanoma, breast and lung cancer." (PMID 32516941, 2020). "Thus, targeting CMTM6 to increase PD-L1 ubiquitination and degradation has a potential value as a therapeutic strategy to improve the immune response of melanoma cells." (PMID 33800394, 2021). "Therefore, CMTM6 is a potential biomarker and therapeutic target for melanoma patients." (PMID 32310824, 2020). "In the meanwhile, there was a strong correlation between the expression of CMTM6 and that of CD3+ T cells, CD20+ B lymphocytes, and CD68+ macrophages in melanoma." (PMID 37726578, 2023). "CMTM6 and CMTM4 expression was found in all malignant melanoma (n = 4) and osteosarcoma (n = 4) samples." (PMID 32596272, 2020). "CMTM6 knockdown leads to decreased expression of PD-L1 in 12 human tumor lines of melanoma, thyroid cancer, colorectal cancer, lung cancer and CML, as well as in three short-term melanoma xenografts." (PMID 38223763, 2024). "Besides, our results demonstrate a positive correlation between elevated levels of CMTM6 and CD58 expression in tumor cells and the clinical benefits in ICB treatment among a cohort of melanoma patients, suggesting potential clinical significance." (PMID 37683639, 2023). "To validate the regulatory role of CMTM6 in CD58 and PD-L1 expression, we conducted CMTM6 deletion and reconstitution in cell lines derived from multiple cancer types, including 8505C thyroid cancer cells, A375 melanoma cells, and RKO colorectal cancer cells." (PMID 37683639, 2023). "Recent studies have shown that CMTM6 combined with its family member CMTM4 can maintain the stability of PD-L1 and prevent PD-L1 from lysosome hydrolyzation in multiple tumor types, such as melanoma, breast cancer, and lung cancer." (PMID 32770259, 2021).